ACTA2 (actin alpha 2, smooth muscle)
Diseases named in the same sentence as ACTA2 in open-access papers (continued):
Sharing a sentence is not in itself a finding about the gene and the disease.
cyst (2 papers, 2019 to 2024). A sac-like closed membranous structure that may be empty or contain fluid or amorphous material. "Despite a reduction in cyst burden, pcy/pcy; Spp1−/− kidneys exhibited increased expression of genes involved in kidney fibrosis, including α‐smooth muscle actin (Acta2), collagen 1 α1‐subunit (Col1α1), and transforming growth factor‐β (TGFβ)." (PMID 39238069, 2024). "Immunoreactivity to ACTA2 was used to determine SMC thickness in the CPAM cyst walls." (PMID 31779656, 2019).
diabetic nephropathies (2 papers, 2020 to 2025). "In diabetic nephropathies, SCX also activates the expression of α-SMA/ACTA2 and bone morphogenetic protein 4, to promote differentiation of mesangial cells into activated myofibroblasts." (PMID 32708589, 2020).
dilated cardiomyopathy (2 papers, 2019 to 2022). Cardiomyopathy which is characterized by dilation and contractile dysfunction of the left and right ventricles. "The differentially expressed genes included several causative genes of congenital heart defects, hypertrophic cardiomyopathy, congenital long-QT syndrome, muscular dystrophy, and dilated cardiomyopathy (e.g., Acta2, Ankrd1, Scn4b, Ano5, Rpl3l, Cenpf)." (PMID 35942699, 2022). "Of note, several iPTGs, such as ACTA2, FHL2, PARD6B, and SLC30A1, may be linked to iASPP-related phenotypes such as sudden cardiac death and dilated cardiomyopathy." (PMID 31395738, 2019).
familial thoracic aortic aneurysm 6 (2 papers, 2022 to 2024). "A number of studies have shown that iris flocculi are caused by a mutation in amino acid 149 of the ACTA2 gene, which can simultaneously lead to familial thoracic aortic aneurysm and dissection (TAAD)." (PMID 39267980, 2024). "In addition, iris flocculi are strongly correlated with familial thoracic aortic aneurysm and dissection (TAAD), which is caused by the mutation of amino acid 149 in the ACTA2 gene." (PMID 39267980, 2024).
gastric tumors (2 papers, 2020 to 2023). "The expression of PTGS2 was independently associated with ACTA2 in non-cancerous tissue, explaining 38% in gene variability, and BCL2 was independently associated with ACTA2 in gastric tumors, explaining 39% in gene variability." (PMID 32630408, 2020). "The expression of ACTA2, HIF1A, and VEGFA was independently associated with TJP1 in non-cancerous tissue, explaining 90% in its variability, and BCL2, HIF1A, CDKN1A, and PTGS2 were independently associated with TJP1 in gastric tumors, explaining 98% in gene variability." (PMID 32630408, 2020).
Gillespie syndrome (2 papers, 2019 to 2024). "For patients with a Gillespie syndrome-like iris, the two known genetic causes are ITPR1 and ACTA2 p.Arg179 substitutions." (PMID 30242502, 2019).
glioma (2 papers, 2022 to 2023). A benign or malignant brain and spinal cord tumor that arises from glial cells (astrocytes, oligodendrocytes, ependymal cells). "This study aimed to investigate the role of ACTA2 in cell migration of glioma cells and determine the impact of ACTA2 expression level on prognosis and recurrence in glioma patients." (PMID 37891844, 2023). "In this study, KD of either ACTC1 or ACTA2 in the U251MG glioma cell line led to shorter cell motion distance." (PMID 37891844, 2023). "Previously, we reported that ACTC1 KD in a malignant glioma cell line reduced cell migration, and the study results suggest that ACTA2 is also involved in glioma cell migration." (PMID 37891844, 2023). "ACTA2 was highly expressed in grade 4 gliomas compared to grade 3 gliomas in clinical malignant glioma specimens, and multiple distant brain lesions were more common in the ACTA2 high expression group." (PMID 37891844, 2023). "When these glioma patients (grades 2–4: n = 667) were divided into two groups by ACTA2 expression, those with high ACTA2 expression (n = 285) had a significantly worse prognosis than those with low expression (n = 382) (p < 0.01)." (PMID 37891844, 2023). "In the clinical glioma samples, ACTA2 expression was remarkably increased in recurrent samples compared to the primary samples from the same patients, and the higher the change in ACTCA2 expression from the start to relapse, the shorter the progression-free survival." (PMID 37891844, 2023). "Furthermore, tumor samples from 12 glioma patients who underwent reoperation at the time of tumor recurrence were utilized to measure ACTA2 expression in the tumors before and after recurrence." (PMID 37891844, 2023). "Comparing ACTA2 expression in initial and recurrent samples from the same glioma patients, we noted that ACTA2/RPL37 increased nearly twofold in recurrent cases (median value: 2.05, range: 0.12–17.39) compared to initial cases (median value: 0.90, range: 0.04–4.10)." (PMID 37891844, 2023). "We observed that in GEMM of gliomas, oncostreams are formed by GFP+ tumor cells, and are enriched in other tumor microenvironment cells such as ACTA2+ mesenchymal cells, IBA1+, and CD68+ tumor associated microglia/macrophages cells, Nestin+ cells and GFAP+ glial derived cells." (PMID 35750880, 2022). "In conclusion, ACTA2 may be involved in distant recurrence in clinical gliomas." (PMID 37891844, 2023). "In the validation cohort study using the TCGA database, WHO grade 4 gliomas (n = 153) had significantly higher ACTA2 gene expression than lower-grade gliomas of WHO grades 2 (n = 226) and 3 gliomas (n = 244) (p < 0.001)." (PMID 37891844, 2023). "In this study, we initially generated U251MG glioma cells in which one of the two α-actin paralog genes, ACTC1 and ACTA2, was knocked down." (PMID 37891844, 2023). "We added U251MG glioma cells with a simultaneous KD of the ACTC1 and ACTA2 genes as “ACTC1/ACTA2-KD cells” in vitro assays to explore the significance of this complementary regulation of ACTC1 and ACTA2 expression." (PMID 37891844, 2023). "Similarly, when restricting the analysis to grade 4 gliomas, a significantly shorter PFS was noted in the group with a higher change in ACTA2 expression (high change group (n = 4): median 5 months (range: 4–7); low change group (n = 3): median 17 months (range: 10–31)) (p = 0.017)." (PMID 37891844, 2023).
Hyperglycemia (2 papers, 2023). An increased concentration of glucose in the blood. "The initiation of EMT in HaCaT cells from hyperglycemia was confirmed by a morphological change, the increased expression of CDH2, KRT10, and ACTA2, and the downregulation of CDH1." (PMID 36827547, 2023). "By 6 months after the onset of hyperglycemia, STZ mice showed visible accumulation of collagen in the upper (3.5-fold; p = 0.001) and lower lobes (4.3-fold; p < 0.0001) of the lung, along with a significant increase in mRNA expression of Acta2 and Ccn2." (PMID 37819895, 2023).
hypertrophic cardiomyopathy (2 papers, 2020 to 2022). A condition in which the myocardium is hypertrophied without an obvious cause. "Genes involved in hypertrophic cardiomyopathy such as Myh6 and Acta2, cardiac fibrosis such as Mmp2 and Col3a1, were all highly up-regulated by AB surgery, and hispidulin treatment significantly down-regulated these genes." (PMID 33324687, 2020).
influenza (2 papers, 2024 to 2025). An acute viral infection of the respiratory tract, occurring in isolated cases, in epidemics, or in pandemics; it is caused by serologically different strains of viruses (influenzaviruses) designated A, B, and C, has a 3-day incubation period, and usually lasts for 3 to 10 days. "The highest density of versican expression observed in untreated and influenza-infected mice was in mesenchymal cells, identified by Col1a1 and Acta2 expression." (PMID 40766376, 2025).
Livedo reticularis (2 papers, 2014 to 2023). A condition characterized by a reticular or fishnet pattern on the skin of lower extremities and other parts of the body. "Shortly thereafter, the gene encoding SMC α-actin (ACTA2) on chromosome 10q22–24 was identified in TAAD families who also had additional symptoms, such as livedo reticularis, patent ductus arteriosus, and iris floccule." (PMID 25104961, 2014).
liver disease (2 papers, 2021 to 2025). "We next examined hepatic stellate cell activation (HSC) as an important mechanism for development of portal hypertension in addition to fibrosis, using quantitative immunostaining for α-smooth muscle actin (Acta2)." (PMID 34513923, 2021).
lymph node metastasis (2 papers, 2017 to 2024). "ACTA2, also known as α-smooth muscle actin (α-SMA), is a key characteristic of CAFs, whose high stromal expression was associated with enhanced angiogenesis, tumor growth, lymph node metastasis, frequency of cancer stem cells and worse clinical outcome." (PMID 38167009, 2024).
malignant glioma (2 papers, 2021 to 2023). A grade III or grade IV glioma arising from the central nervous system. "We aimed to highlight actin alpha 2, smooth muscle (ACTA2) as potential biomarkers of brain invasion and distant recurrence in malignant gliomas." (PMID 37891844, 2023). "The present study shows that ACTA2 expression is a factor in the mechanism of malignant glioma recurrence and represents a challenge for future elucidation of the mechanism of malignant glioma recurrence and control." (PMID 37891844, 2023). "The present study revealed that ACTA2 is an important migratory factor in malignant gliomas and is involved in recurrence." (PMID 37891844, 2023). "Elucidation of the migration mechanism in malignant gliomas is crucial in developing future therapeutic regimens, and ACTA2 is a promising candidate as a therapeutic target." (PMID 37891844, 2023). "One of the migration factors in malignant gliomas is ACTA2, and one hypothesis for the involvement of ACTA2 in recurrence is that cells showing a higher ACTA2 expression may migrate and invade deeper into the brain and escape surgical resection." (PMID 37891844, 2023). "Using the human malignant glioma cell line, U251MG, we generated ACTA2 knockdown (KD) cells treated with small interfering RNA, and the cell motility and proliferation of the ACTA2 KD group were analyzed." (PMID 37891844, 2023). "EMT, as a key factor of malignant glioma invasion enhancement, can be characterized by an increase in the expression of biomarkers, such as CDH2, VIM, FN1, SNAI1, SNAI2, ACTA2, and so on." (PMID 34034744, 2021).
myelofibrosis (2 papers, 2022 to 2024). A partial or complete replacement of the bone marrow stroma by fibrous tissue. "Myelofibrosis MSCs were transcriptionally distinct, with significant enrichment of genes and pathways associated with myofibroblast transition including Acta2, KRAS and phosphoinositide-3-kinase (PI3K) signaling, inflammatory response genes and IL2-STAT5 signaling." (PMID 39383242, 2024). "Increased α-smooth muscle actin (Acta2) expression has been reported in myelofibrosis." (PMID 35439167, 2022).
nephritis (2 papers, 2017 to 2018). Inflammation of renal tissue. "Glomerular gene expression of Tgfb1, α-smooth muscle actin (Acta2), fibronectin (Fn1) and integrin αv (Itgav) was increased in control mice with nephritis and this increase was reduced in Rosa-CTGF cKO mice with nephritis." (PMID 28191821, 2017). "Tgfb1, Acta2, Fn1 and Itgav mRNA expression in the glomeruli was increased in control mice with nephritis, and this increase was reduced in Pdgfra-CTGF cKO mice with nephritis." (PMID 28191821, 2017). "In control mice with nephritis, Ctgf, Tgfb1, Acta2, Fn1, and Itgav mRNA expressions in the glomeruli were increased compared with control mice without nephritis." (PMID 28191821, 2017). "In addition to the increases in the expression levels of fibrotic makers such as Tgfβ1, Acta2, and Fn1, the glomerular mRNA expression of MCP-1 (Ccl2) and F4/80 (Adgre1) is increased in the control mice with anti-GBM nephritis, and this increase is reduced in the Rosa-CTGF cKO mice with nephritis." (PMID 30123390, 2018). "Expression of Fn1, Acta2, Tgfb1, Adgre1 or Ccl2 was tended to be reduced in Rosa-CTGF cKO mice with nephritis, but not significant." (PMID 28191821, 2017).
pancreatitis (2 papers, 2021 to 2023). Inflammation of the pancreas. "Interestingly, gene expression analysis of Acta2 at 72h after the onset of pancreatitis confirmed the significant difference between Tbx3-KO (epi) and control mice." (PMID 36941669, 2023). "Significantly reduced damage was further substantiated by lower collagen content, alpha smooth muscle actin staining (ACTA2), and transforming growth factor β (Tgfb1) expression in Dkk3‐null animals 96 h after pancreatitis induction, indicating less fibrosis at this time point." (PMID 34306986, 2021).
abdominal aortic aneurysm (1 paper, 2022). Enlargement and ballooning of the vessel that supplies arterial blood to the abdomen, pelvis and legs. "Additionally, small samples size and wide variation in gene expression profiles for some genes limit the conclusions that can be made; however, consistent changes in Acta2 in smooth muscle deficient Lpp3 mice highlight a role for smooth muscle Lpp3 in AngII mediated abdominal aortic aneurysm." (PMID 35383201, 2022).
alveolitis (1 paper, 2025). "Importantly, blocking the C5a/C5aR1 signaling either before or after the initiation of fibrosis led to significant reductions in lung tissue cell numbers, alveolitis scores, Ashcroft scores, collagen deposition, and the expression of fibrosis-related genes, including Acta2, Col1a1, Col3, and Fn1." (PMID 40867551, 2025).
anaplastic carcinomas (1 paper, 2025). "A single study included also a small set of PDC reported the expression of CAF-associated markers (collagen type 1 gene, COL1A1, and alpha smooth muscle actin gene, ACTA2) in such cases, similar to papillary and anaplastic carcinomas." (PMID 39849146, 2025).
autoimmune vasculitis (1 paper, 2024). An autoimmune form of vasculitis. "It is also possible that people with ACTA2 variants have an increased risk of pulmonary hemorrhage at baseline, as seen in people with autoimmune vasculitis and Goodpasture syndrome." (PMID 39310919, 2024).
bladder tumor (1 paper, 2023). "qRT-PCR demonstrated that the mRNA expression levels of ACTA2, FLNA, TAGLN, and TPM1 in bladder tumor cells were significantly decreased compared with normal bladder cells, which corresponded to the results of our prior bioinformatic investigation using public datasets." (PMID 37274283, 2023). "In addition, qRT-PCR and Western blotting demonstrated that the transcription and translation levels of ACTA2, FLNA, TAGLN, and TPM1 were much lower in bladder tumor cells than in normal bladder cells." (PMID 37274283, 2023).
cerebral artery disease (1 paper, 2023). "ACTA2 triggers cerebral artery disease with abnormal internal carotid circulation coupled with proximal segmental dilatation, distal segmental occlusive disease and prolonged dilatation, predisposes children to IS." (PMID 37794518, 2023).
cervical cancer (1 paper, 2023). A primary or metastatic malignant neoplasm involving the cervix. "We found that CAF markers, such as fibroblast activation protein (FAP), ACTA2 (α-SMA), and beta-type platelet-derived growth factor receptor (PDGFRB) were associated with the infiltration of macrophages in cervical cancer in the Tumor Immune Estimation Resource (TIMER) database." (PMID 36900416, 2023).
cholangiocarcinoma (1 paper, 2024). A carcinoma that arises from the intrahepatic biliary tree (intrahepatic cholangiocarcinoma) or from the junction, or adjacent to the junction, of the right and left hepatic ducts (hilar cholangiocarcinoma). "Fib-C3 cells were like the vascular cancer-associated fibroblasts (vCAFs) in the intrahepatic cholangiocarcinoma and exhibited high expression levels of ACTA2, RGS5, MYH11, and EPAS1." (PMID 39107908, 2024).
ciliopathy (1 paper, 2025). A genetic disorder of the cellular cilia or the cilia anchoring structures, the basal bodies, or of ciliary function. "For the other two IDA-related genes (Acta2, Cfap100/Ccdc37) and one RS-related gene (Morn3), no ciliopathy has been linked to mutations of these three genes so far." (PMID 40568142, 2025).
congenital heart malformation (1 paper, 2019). A disease that has its basis in the disruption of heart development. "Many congenital heart malformations associated with ACTA2 mutations might however be difficult to detect prenatally on ultrasound (e.g. patent ductus, bicuspid valve)." (PMID 31752940, 2019). "If the genetic status of the foetus is unknown or the foetus carries an ACTA2 mutation, standardized cardiac ultrasound of the foetus around a gestational age of 20 weeks should be offered due to the slightly increased risk of congenital heart malformations." (PMID 31752940, 2019).
coronary artery stenosis (1 paper, 2014). "In the present study, the correlation between SNPs in the promoter region of the ACTA2 gene and coronary artery stenosis in patients with T2DM was investigated, and the interaction of SNPs with plasma insulin was further analyzed." (PMID 24669260, 2014). "In conclusion, to the best of our knowledge, this study is the first to demonstrate a significant correlation between the rs1324551 GG genotype in the ACTA2 gene and coronary artery stenosis in patients with T2DM." (PMID 24669260, 2014). "In conclusion, the rs1324551 SNP in the promoter region of the ACTA2 gene was identified to be independently correlated with the degree of coronary artery stenosis in patients with T2DM and plasma insulin may inhibit coronary artery stenosis during the pathogenic process." (PMID 24669260, 2014).
COVID-19 (1 paper, 2022). A disease caused by infection with severe acute respiratory syndrome coronavirus 2. "By screening the marker genes of early stage EndMT, the marker gene at the early stage was finally identified as ACTA2 with an SMD of 0.87,95% CI (0.23,1.51) for COVID-19 vs. control in 5 GEO datasets following meta-analysis." (PMID 36248845, 2022).
dementia (1 paper, 2023). Loss of intellectual abilities interfering with an individual's social and occupational functions. "Further, we identified ACTA2, LTBP2, and NCS1 as potential contributors to dementia risk." (PMID 38016990, 2023).
Dupuytren’s disease (1 paper, 2023). "In myofibroblasts from patients with Dupuytren’s disease (DD), a localized fibrotic disorder of the palm, A485 inhibited the profibrotic genes ACTA2 and COL1A1 expression." (PMID 37569677, 2023). "In myofibroblasts from Dupuytren’s disease patients, SGC-CBP30 and I-CBP112 were used to validate CREBBP and EP300 as key regulators of the profibrotic phenotype in myofibroblasts by decreasing the expression of the profibrotic genes ACTA2 and COL1A1." (PMID 37569677, 2023).
dyslipidemia (1 paper, 2019). "Patients with a pathogenic variant in ACTA2 should be managed according to standard strategies for other cardiovascular risk factors, including dyslipidemia." (PMID 31752940, 2019).
E. coli infection (1 paper, 2025). "However, under the condition of E. coli infection, ACTA2 and procollagen 1 (proCOL1) co-expressing cells are rare in the mouse and canine prostate, prompting us to test whether proCOL1 and ACTA2 co-expressing cells are also rare in histologically inflamed human prostate." (PMID 39748675, 2025).
endometrial polyp (1 paper, 2024). A benign nodular lesion protruding above the surface of the endometrium. "Relevant critical genes were downregulated in endometrial polyps, including ACTA2, KCNMB1, KCNMB2, PPP1R12B, MYL9, and ACTG2." (PMID 38473810, 2024).
Esophageal stricture (1 paper, 2023). A pathological narrowing of the esophagus that is caused by the development of a ring of scar tissue that constricts the esophageal lumen. "Furthermore, TGF-β1, Col1a1, and Acta2 were found to be increased in the tissue with esophageal stricture based on PCR and histological analysis." (PMID 37474710, 2023).